GSDME (gasdermin E)
Diseases named in the same sentence as GSDME in open-access papers (continued):
Sharing a sentence is not in itself a finding about the gene and the disease.
tumor (continued). "In this study, we successfully designed and synthesized three PtIV prodrugs, MRP, DRP, and HRP, that could induce pyroptosis in tumor cells by activating the Caspase‐3/GSDME pathway." (PMID 40432601, 2025). "By uncovering the anti-tumor and immune-related mechanisms of fosinopril via GSDME-mediated pyroptosis, this work offers new insights for developing low-toxicity, high-efficiency anti-cancer therapies and highlights potential breakthroughs in the clinical treatment of NSCLC." (PMID 41271670, 2025). "In addition, GSDME promotes tumor suppression by activating pyroptosis and enhancing antitumor immunity." (PMID 39917567, 2025). "Notably, granzyme B also facilitates the cleavage of GSDME into its active N-terminal fragment (N-GSDME), amplifying pyroptosis in tumor cells." (PMID 41239499, 2025). "Current studies face three major challenges: elucidating the mechanisms underlying GSDME overexpression in HCC, clarifying the molecular hubs of pyroptosis-independent pro-tumor pathways, and developing precision strategies to control the functional switch of GSDME." (PMID 40568597, 2025). "ORFV-triggered GSDME-mediated tumor pyroptosis recruits CTLs to the TME." (PMID 40721578, 2025). "Furthermore, substantial evidence indicates that reactive oxygen species (ROS) plays a critical role in driving GSDME-mediated pyroptosis via mitochondrial oxidative damage, thereby exhibiting anti-tumor effects." (PMID 40523886, 2025). "Elevated TMAO levels correlate with increased CD8+ T cell infiltration, and mechanistic studies demonstrate that TMAO induces gasdermin E (GSDME)-mediated pyroptosis in tumor cells, releasing inflammatory cytokines that further activate tumor-specific CD8+ T cells." (PMID 41355895, 2025). "Correspondingly, the knockdown of GSDME (DFNA5) reduced the anti-tumor activity of Tc3." (PMID 39816682, 2025). "Recent studies have also revealed the critical regulatory role of GSDME in tumor immunotherapy." (PMID 40568597, 2025). "Interestingly, if drugs such as oxaliplatin are used to activate the caspase-3/GSDME pathway, the pyroptosis process can be restarted, promoting T cells to enter the tumor area and exert their effects." (PMID 40568597, 2025). "GSDME also localizes to the nucleus of pancreatic ductal adenocarcinoma (PDAC) tumor cells to act both as a transcriptional regulator and as a transporter to mediate the entry of the transcription factor Y‐box‐binding protein 1 (YBX1) and promote mucin expression." (PMID 40783818, 2025). "In case of CRC also, GSDME has been shown to have anti-tumor effect." (PMID 39062587, 2024). "However, researchers have also found that in epithelial-derived cells, especially in tumor cells, the induction of pyroptosis is mainly mediated by GSDME, which is activated by caspase-3/8 and other apoptosis-related caspases." (PMID 39215364, 2024). "The purpose of this study was to determine the mechanism of GSDME-mediated anti-tumor immunity in CRC and whether it benefited the efficacy of ICIs." (PMID 38853246, 2024). "In addition, cleavage of GSDME by GZMB promotes tumour cell death and enhances the establishment of anti‐tumour immune effects." (PMID 38652105, 2024). "In addition, several studies have shown that GSDME, as a molecule with known anti-tumor potential, is involved in the development and progression of many cancers." (PMID 39062587, 2024). "For example, a biomimetic nanoparticle (BNP) could efficiently accumulate at tumor sites, induce GSDME-mediated pyroptosis, and activate systemic anti-tumor immunity, effectively reducing the severe toxicity to normal cells and tissues." (PMID 39062587, 2024). "Upregulation of GSDME expression increases the number of natural killer and CD8+ T lymphocytes in the tumor microenvironment and enhances the phagocytic activity of tumor-associated macrophages against tumor cells." (PMID 39526199, 2024).
tumor (continued). "However, most tumor cells are restricted from activating pyroptosis due to low expression of the key protein GSDME in the pyroptosis pathway." (PMID 40630838, 2024). "Similarly, granzyme B (GZMB) from these immune cells can also initiate GSDME-dependent apoptotic cell death in tumor cells through caspase-3-mediated cleavage of GSDME." (PMID 39723212, 2024). "Considering the importance of GSDME activation in chemotherapy-induced tumor cell death, these findings raise the possibility that antitumor drugs like cisplatin (a first-line drug of NB chemotherapy) could induce pyroptosis in NB cells." (PMID 38177154, 2024). "Similarly, miltirone, a quinone derivative extracted from S. miltiorrhiza, induces pyroptosis in HCC cells by promoting GSDME hydrolysis and caspase-3 activation, thus facilitating tumor cell death." (PMID 39117626, 2024). "Caspase-3/GSDME-dependent pyroptosis is a key determinant of anti-tumor immunity." (PMID 38584157, 2024). "GSDME expression was significantly and negatively correlated with the tumor purity of LIHC (p < 0.05), while it was significantly and positively correlated with the degree of infiltration of B cells, CD8+ T cells, CD4+ T cells, macrophages, neutrophils and dendritic cells." (PMID 38434972, 2024). "This study highlighted that ANPS targeting early endosomes could specifically activate phospholipase C (PLC) signaling on the endosomal membrane and the downstream caspase-3/GSDME pathway, leading to efficient tumor cell pyroptosis." (PMID 39221221, 2024). "However, the initiation of pyroptosis requires a high level of GSDME expression, and the proportion of GSDME in tumor cells is low due to epigenetic gene silencing." (PMID 38902235, 2024). "When GSDME is highly expressed, it is cleaved by active caspase‐3, and the released N‐terminal domain perforates on the cell membrane, leading to cell swelling, rupture and death for tumor pyroptosis." (PMID 37984863, 2024). "GSDME also induced pyroptosis of tumor cells during oncolytic viral cancer therapy: oncolytic parapoxvirus ovis reduced ubiquitination of GSDME and stabilized it to initiate pyroptosis of tumor cells expressing low levels of GSDME95." (PMID 38195694, 2024). "Notably, GSDME is silenced in multiple tumors through GSDME DNA methylation, and therefore, methyltransferase inhibitors (e.g., decitabine) can increase GSDME expression and inhibit tumor growth." (PMID 38799433, 2024). "ROS generated by P18 after laser irradiation together with the chemotherapy drug PTX could jointly induce rapid and persistent pyroptosis by upregulating GSDME in tumor cells." (PMID 39221221, 2024). "In tumor immunity, when cancer cells endogenously or extracellularly express GSDME, activated caspase 3 induced by various chemotherapy drugs can further cleave and activate GSDME, triggering ‘secondary apoptosis’." (PMID 38238307, 2024). "Specifically, caspase 3/GSDME cleavage-mediated pyroptosis in tumor cells has provided a new understanding that anticancer drugs inducing apoptosis may also have the potential to induce pyroptosis." (PMID 39138191, 2024). "The authors suggested that ROS generation of radiation could activate pyroptosis via GSDME/caspase-9/caspase-3 pathway in addition to apoptosis, which could further activate an anti-tumor immune response." (PMID 39398428, 2024). "Meanwhile, GSDME suppresses tumor growth by activating anti-tumor immunity in many mouse models." (PMID 38853246, 2024). "Notably, GSDME-deficient tumors had reduced T cell infiltration and tumor cell clearance but restoring GSDME processing resulted in pyroptosis and delayed tumor growth." (PMID 38391959, 2024).
tumor (continued). "Moreover, emerging research indicates a potential correlation between the fusion of mRNA-lncRNA, leading to the production of the chimeric protein EPS15L1-lncOR7C2-1, which facilitates tumour growth by potentially controlling GSDME-related pyroptosis." (PMID 39267831, 2024). "mRNA expression levels of GSDMC and GSDME were correlated to tumor purity." (PMID 39607202, 2024). "The methylation inhibitor 5-aza-2′-deoxycytidine (5-aza-dC) could promote GSDME expression and inhibit tumor cell proliferation and carcinogenesis, implying that GSDME is a potential tumor suppressor gene in CRC." (PMID 39062587, 2024). "The GSDME protein plays a central role in modulating the tumor microenvironment." (PMID 39526199, 2024). "In conjunction with previously verified mechanisms of Mn-ZrMOF+MW inducing ROS, this suggests that during Mn-ZrMOF@DAC+MW treatment, DAC loaded in Mn-ZrMOF@DAC can be released into tumor cells, up-regulating GSDME protein, and massive ROS production post-MW radiation can activate caspase-3." (PMID 40630838, 2024). "In CT26 animal model, either GSDME or αPD1 didn’t show inhibition of tumor growth." (PMID 38853246, 2024). "We could find that GSDME expressed both in intestinal epithelium and stroma cells and was downregulated in tumor tissues." (PMID 38853246, 2024). "Furthermore, studies on pyroptosis are focusing on inducing tumor cell pyroptosis by GSDME cleavage." (PMID 38229080, 2024). "This GSDME-dependent pyroptosis could convert chemotherapy-induced cell death from non-immunogenic apoptosis to immunogenic pyroptosis and augment anti-tumor immune responses in preclinical models." (PMID 38191648, 2024). "According to a recent study, ectopic expression of GSDME in cancer cells could enhance anti-tumor immune responses and suppress tumor growth." (PMID 39062587, 2024). "For example, reduced GSDME expression has been shown to compromise the effectiveness of anti-tumor treatments, while increased GSDME expression could potentially enhance the efficacy of these therapies." (PMID 38756442, 2024). "To elaborate, TMAO can elicit gasdermin E (GSDME)-mediated pyroptosis in tumor cells." (PMID 38397971, 2024). "Ultimately, owing to the cooperative of GSDME protein from tumor self-supply and cisplatin induced activation of caspase-3, powerful tumor pyroptosis was initiated precisely and efficiently, further reversing the immunosuppressive TME and boosting the antitumor immune cascade as positive feedback." (PMID 36774382, 2023). "It was found that increasing the expression of GSDME induced tumor cell pyroptosis." (PMID 36867605, 2023). "Furthermore, the expression of gasdermin E (GSDME) can enhance tumor cell phagocytosis by TAMs and increase the number and function of tumor-infiltrating NK cells and CD8 + T lymphocytes." (PMID 38012150, 2023). "However, recent studies have shown that chemotherapeutic drugs can induce pyroptosis in tumor cells with high GSDME expression." (PMID 36867605, 2023). "Described processes further support the anti-tumor function of GSDME." (PMID 37771587, 2023). "However, recent studies have shown that chemotherapeutic drugs induce pyroptosis of tumor cells, in which activated caspase-3 cleave specific sites of pyroptosis-related protein GSDME to generate a GSDME-N terminal domain." (PMID 36867605, 2023). "Further evidence suggests that GSDME is indeed involved in tumor biology, and its level of expression may lead to changes in treatment strategies." (PMID 36867605, 2023). "Therefore, identifying strategies for elevating GSDME levels in tumors to further accelerate GSDME-mediated cell pyroptosis are promising approaches for effective tumor clearance." (PMID 36641456, 2023). "GSDME supports anti-tumor immunity, and its expression is often suppressed in cancer." (PMID 37771587, 2023).
tumor (continued). "Moreover, the overexpression of GSDME enhances the phagocytic capacity of TAMs and increases both the number and antitumor activity of tumor-infiltrating CD8+ T lymphocytes and NK cells." (PMID 38066523, 2023). "However, recent studies have unveiled that caspase 3 can catalyze the cleavage of GSDME, leading to the production of N-GSDME termini and consequent pyroptosis in tumor cells." (PMID 37753070, 2023). "Additionally, the xenograft models were constructed to assess the role of GSDME on tumor growth in vivo, by injecting SK-Hep1 cells into nude mice following transfection with sh-NC or sh-GSDME." (PMID 37149620, 2023). "In fact, GSDME-mediated pyroptosis has a dual effect on tumor immunotherapy." (PMID 38104141, 2023). "The expression of GSDME is suppressed in many cancers, and such repression could enhance tumor growth but decrease survival." (PMID 37134086, 2023). "Additionally, ionizing radiation can induce tumor immunity through pyroptosis, which is mediated by GSDME." (PMID 37705746, 2023). "Moreover, Granzyme B (Gzm B) can cleave GSDME in an indirect manner by activating caspase-3, or it can also directly cleave GSDME to initiate pyroptosis, which provides a new therapeutic strategy for future tumor immunotherapy." (PMID 36823153, 2023). "JTC801 activated caspase‐3 to cleave GSDME, triggering tumor pyroptosis." (PMID 37933240, 2023). "Research on both in vitro and in vivo models has shown GSDME to have a tumor-repressive role." (PMID 37705746, 2023). "Notably, GSDME protein levels in tumor cells increased upon ORFV (MOI = 1) treatment at indicated time points (6 hpi (hours post inoculation) for B16 cell and A549; 12 hpi for 4T1)." (PMID 36641456, 2023). "Furthermore, tumors with lymphatic vessel invasion and advanced tumor-node-metastasis (TNM) stage exhibited an increase in GSDME promoter methylation." (PMID 38104141, 2023). "CTLs can induce pyroptosis in human GSDME or GSDMB-sensitized tumor cells." (PMID 37705746, 2023). "As a tumour suppressor, GSDME enhances antitumour immunity by activating cellular pyroptosis." (PMID 36600313, 2023). "The detection of GSDME protein in mouse tumour by western blot also found that the group with overexpression of CPA4 could inhibit the occurrence of pyroptosis in tumor tissues compared with the control group." (PMID 38049405, 2023). "Recent research indicates that CAR-T cells could activate the caspase-3/GSDME signaling pathway in B leukemia cells by releasing significant amounts of perforin and GzmB, which induce pyroptosis and enhance anti-tumor immunity." (PMID 38104141, 2023). "Previous studies have shown that GSDME is downregulated in some human cancers and might act as a tumor suppressor." (PMID 36920176, 2023). "Importantly, the GSDME protein level was increased upon ORFV challenge in tumor cell lines, primary human tumor tissues and in vivo murine tumors, which was owing to the decrease of ubiquitination on GSDME." (PMID 36641456, 2023). "Thus, it is vital to illustrate the upstream regulation of GSDME to further utilize the immunogenic effects of pyroptosis to boost the anti-tumor effects of immune therapy." (PMID 37528490, 2023). "In conjunction with anti-PD-1 therapy, PDNP induces GSDME-mediated pyroptosis and enhances the immune response in solid tumors, effectively halting invasive metastasis and extending survival due to its remarkable anti-tumor immunity." (PMID 38104141, 2023). "Moreover, once activated, GSDME has the potential to turn a “cold” tumour into a “hot” tumour, which can be recognized and controlled by the immune system." (PMID 36702978, 2023). "As a tumor suppressor, GSDME activates pyroptosis and enhances anti-tumor immunity." (PMID 37077542, 2023). "Tumor-associated macrophages are involved in pyroptosis through the classical pathway induced by the caspase-1 cleavage of GSDMD and the pathway mediated by the caspase-8 cleavage of GSDME and the granzyme action of GSDMB." (PMID 37542283, 2023).
tumor (continued). "In fact, GSDME-mediated pyroptosis performs a dual role in anti-tumor therapy." (PMID 38104141, 2023). "However, scientists reported that GSDME was highly expressed in only 1/10 of tumor cells, but 3/5 of normal human cells exhibited rich expression of GSDME." (PMID 38016064, 2023). "However, in tumors expressing GSDME, pyroptosis produces DAMPs that can recruit immune cells to the tumor microenvironment, and GSDME expression greatly increases the number of tumor-infiltrating lymphocytes (TILs) and macrophage phagocytosis." (PMID 36605484, 2023). "In addition, the expression of GSDME was shown to be upregulated in tumor cells after treatment with decitabine, contributing to pyroptosis and promoting cancer cells’ sensitivity to chemotherapy agents." (PMID 38016064, 2023). "This is enough to prove that GSDME has a tumor-suppressive effect." (PMID 37705746, 2023). "GSDME, caspase 3, and caspase 8 are more abundantly expressed in tumor tissue." (PMID 37752941, 2023). "In 2017, scientists reported that chemotherapy could switch cell death from apoptosis to pyroptosis via caspase-3-induced GSDME cleavage in tumor cells with high GSDME expression." (PMID 38016064, 2023). "GSDME is generally downregulated in tumor tissues and cells." (PMID 37085908, 2023). "TMPs inject methotrexate into cholangiocarcinoma cells (CCA), induce GSDME-mediated pyroptosis, activate patient-derived macrophages to produce pro-inflammatory cytokines, and recruit neutrophils to tumor sites for performing drug-directed tumor destruction." (PMID 37705746, 2023). "Notably, GSDME was recently shown to be cleaved and activated by caspase-3 with a role in anti-tumor immunity, driving chemotherapy drug-induced normal-tissue damage or viral infection-mediated secondary necrosis as confirmed by STRING analysis." (PMID 35795683, 2022). "GSDME, located on chromosome 7p15 and also named deafness autosomal dominant 5 (DFNA5) due to its association with hereditary hearing loss, has been implicated as a putative tumour suppressor." (PMID 35517821, 2022). "Therefore, therapies targeting GSDME harbor great prospects in enhancing anti-tumor efficacy and reducing toxic and side effects." (PMID 35462927, 2022). "However, GSDME often has the characteristics of expression inhibition in the process of tumor occurrence and development, and genetic screening and microarray analyses showed a hypermethylation in the GSDME DNA promoter region." (PMID 36612023, 2022). "GSDME is highlighted in cancer for its suppressive activity on the tumor." (PMID 35819638, 2022). "Some researchers have reported that the protein expression of GSDME in normal tissues is much higher than in tumor tissues, which may be related to the methylation of the GSDME gene promoter in tumor cells." (PMID 36612023, 2022). "However, it is worth noting that GSDME has been widely overexpressed in normal cell while most tumor cells tend to express low GSDME due to GSDME gene promoter methylation." (PMID 36209102, 2022). "The in vivo xenograft tumor model further confirmed that GSDME upregulation could promote carboplatin-induced tumor cell death." (PMID 35480866, 2022). "Additionally, the cell-killer granzyme B (GZMB) is released to tumor cells by cytotoxic lymphocytes, followed by cleavage of GSDME by GZMB, inducing tumor cell pyroptosis." (PMID 36189207, 2022). "GSDME was expressed at high levels in human PDAC tumour cell lines." (PMID 35292781, 2022).